GNAS (GNAS complex locus)
Diseases named in the same sentence as GNAS in open-access papers (continued):
Sharing a sentence is not in itself a finding about the gene and the disease.
neural tube defect (1 paper, 2020). A congenital defect characterized by failure of the neural tube to close completely; this results in the presence of openings in the brain or spinal cord. "Abnormal methylation of GNAS has also been shown to lead to neural tube defects (NTDs) during pregnancy, and even to embryonic development failure." (PMID 32153632, 2020).
nodular toxic goiter (1 paper, 2025). "Activating germline mutations in GNAS may cause McCune–Albright syndrome resulting in a multinodular toxic goiter, where activating germline mutation in TSHR causes nonautoimmune hyperthyroidism with or without nodular lesions within the thyroid." (PMID 39189533, 2025).
peritoneal disease (1 paper, 2024). "Survival was significantly associated with the grade of the primary neoplasm, the grade of the peritoneal disease, the completeness of cytoreduction score and with mutation in either GNAS, KRAS or both." (PMID 39435876, 2024).
primary adrenal insufficiency (1 paper, 2022). A hormonal disorder that occurs when the adrenal glands fail to release adequate amounts of glucocorticoids (cortisol), mineralocorticoids (aldosterone, 11-deoxycorticosterone), and androgens (dehydroepiandrosterone) to meet physiologic needs, despite release of ACTH from the pituitary. "We report this case to highlight that GNAS mutation is an unusual cause of primary adrenal insufficiency." (PMID 35927642, 2022). "GNAS mutation is easily overlooked as a rare cause of primary adrenal insufficiency." (PMID 35927642, 2022). "Here we firstly report a neonatal case of primary adrenal insufficiency caused by GNAS mutation." (PMID 35927642, 2022).
primary immunodeficiency (1 paper, 2024). "Similarly, GNAS is upregulated and enriched in three pathways, including the primary immunodeficiency pathway, the VEGF signalling pathway, and the intestinal immune network for IgA production pathway." (PMID 39344484, 2024).
renal tubular diseases (1 paper, 2025). "Whole-exome sequencing (WES) was used to exclude mutations in genes associated with renal tubular diseases, and methylation-sensitive multiplex ligation-dependent probe amplification (MS-MLPA) was employed to assess GNAS methylation status." (PMID 40893942, 2025).
schizophrenia (1 paper, 2014). A major psychotic disorder characterized by abnormalities in the perception or expression of reality. "Further, it would be interesting to examine the role of APOA-I and GNAS in first episode schizophrenia treated with those antipsychotic medications that have higher risk of metabolic side effects, such as olanzapine." (PMID 24710015, 2014). "The present study found a significant down-regulation of GNAS in schizophrenia patients after 8 weeks of risperidone treatment." (PMID 24710015, 2014).
somatotrophinomas (1 paper, 2020). "AHR may also have AIP-independent roles in pituitary tumorigenesis as AHR but not AIP expression is reduced in GNAS-mutated somatotrophinomas, and AHR activation increases the transcription of CDKN1B, which is another tumour suppressor gene implicated in pituitary and other endocrine tumours." (PMID 31996203, 2020).
thyroid tumor (1 paper, 2022). A benign or malignant neoplasm affecting the thyroid gland. "The prevalence of GNAS mutations in TC ranges from 0.22%—2.12% according to an investigation in 1841 human thyroid tumors." (PMID 36151521, 2022). "In the COSMIC database, 73 of 3724 thyroid tumors capture mutations in the GNAS gene, but all at different locations." (PMID 36151521, 2022). "GNAS aberrations have been identified not only in thyroid tumors, but also in many other tumors in humans." (PMID 36151521, 2022).
transient neonatal diabetes mellitus (1 paper, 2019). Transient neonatal diabetes mellitus (TNDM) is a genetically heterogeneous form of neonatal diabetes (NDM) characterized by hyperglycemia presenting in the neonatal period that remits during infancy but recurs in later life in most patients. "Other overlapping molecular findings are 6q24 alterations, linking transient neonatal diabetes mellitus (TNDM) and BWS, and variants in 20q13 affecting the GNAS locus which are detectable in SRS." (PMID 31466347, 2019).
tumor (227 papers, 2003 to 2026). "Mutations in the KRAS and GNAS oncogenes are common, but the reported frequencies vary greatly, most likely because of low tumor cellularity in peritoneal tumor samples." (PMID 41868810, 2025). "Kirsten rat sarcoma viral oncogene homolog (KRAS) and GNAS mutations are frequently found in mucinous neoplasms of the pancreas and appendix, suggesting a role in tumor initiation and progression." (PMID 40319316, 2025). "Based on the description of mutations in several tumor types, GNAS occurs most frequently in appendix malignancies (70%) and pituitary tumors (27%), and it is mutated in around 5% of sequenced tumors." (PMID 40969301, 2025). "The overexpression of GNAS is associated with increased cAMP levels, promoting tumor formation, metastasis, and progression in cancer." (PMID 40943367, 2025). "This research offers a thorough analysis of the clinical features of patients with GNAS mutations in a Chinese cohort, revealing pronounced secretory functions and reduced tumor dimensions in GH-secreting adenomas with GNAS mutations." (PMID 39513543, 2025). "Previous studies have delineated the link between smaller tumor volumes and GNAS mutations, but mentions of lower Ki-67 indexes are scarce." (PMID 39513543, 2025). "Hotspot activating mutations (R201 and Q227) and amplifications of GNAS have been identified in human tumor types including pituitary, pancreatic, colorectal, and TC64." (PMID 41353477, 2025). "Typically, patients bearing GNAS mutations present with smaller tumor sizes, higher GH and insulin-like growth factor 1 (IGF-1) levels and better responses to neurosurgeries." (PMID 39513543, 2025). "Only one case was misclassified as benign; this misclassified tumor is a somatotroph with a GNAS R201S mutation that has grown indolently following radiotherapy." (PMID 38758238, 2024). "The prevalence of GNAS mutations in ‘MS + Bone’ and ‘MT + Tumor’ subgroups was 67% (95% CI = 42%–88%; n = 187) and 64% (95% CI = 24%–95%; n = 15; two studies), respectively." (PMID 39135681, 2024). "Numerous studies have indicated that the presence of point mutations in GNAS strongly reflects the biological characteristics of GHPAs, such as tendency for densely granulated tumors and smaller tumor size." (PMID 38827318, 2024). "In summary, we demonstrated that low GNAS expression was associated with high baseline tumor-intrinsic TE expression and a pro-IFN state in DLBCL patients, suggesting its potential role in viral mimicry priming." (PMID 39117798, 2024). "Mutations in GNAS were scanned by directly sequencing genomic PCR products amplified from the tumor samples of patients using specific primer sets." (PMID 38827318, 2024). "The biology of GNAS mutation showed an elevated level of invasiveness, characterized by irregular tumor shape, ambiguous tumor boundaries, multiple nodules affecting both lobes or the entire thyroid gland, and distant metastases (p<0.05)." (PMID 38904052, 2024). "The best recognized tumor-driving molecular changes in somatotroph PitNETs are activating mutations in the GNAS gene." (PMID 39497133, 2024). "The results of clustering by CCF suggested a decrease in intratumoral heterogeneity and an increase in the fraction of tumor cells harboring the GNAS mutation, indicating clonality during progression from LGASC to MSC." (PMID 37650999, 2023). "Over the last decade, tumor sequencing and mouse modeling studies have demonstrated the importance of GNAS/PKA signaling in cancer, including frequent oncogenic mutations in GNAS across multiple tumor types." (PMID 36692000, 2023). "In the reviewed studies, GNAS mutations were identified in both low-grade and high-grade neoplasms at high frequencies (ranging 31–100%), and the most common variants were R201C and R201H." (PMID 36723696, 2023). "We recently reported that GNAS mutations inhibit tumor cell invasion by suppressing the KRAS pathway in PDAC." (PMID 37470859, 2023).
tumor (continued). "KRAS and/or GNAS mutations are found in >90% of IPMNs, both in those with advanced neoplasia (high-grade dysplasia or adenocarcinoma) and low-grade dysplasia." (PMID 36980608, 2023). "Our somatic mutation profiling of the tumors identified a somatic missense mutation in the GNAS gene, which is present in 4 of 7 tumor WGS samples and 20 of 32 tumors of GLPs genotyped by sanger sequencing." (PMID 36151521, 2022). "Each tumor subtype has a distinct molecular profile including gene expression pattern and frequency of GNAS mutations as well as profile of diagnostic histological features based on results of immunohistochemical staining and electron microscopy." (PMID 36497102, 2022). "There was only one missense mutation p.A204D (chr24:43657087C > A) in the GNAS gene (exon 9), which was identified in 4 of 7 tumor samples." (PMID 36151521, 2022). "Further, in the tumour stages, the “late stage” (stages 3 & 4) had more GNAS gene mutation (68%) than the early stage (27%)." (PMID 36428574, 2022). "Mutations in the GNAS gene are frequently observed in a variety of malignant, premalignant, and benign tumors and in tumor-derived organoids and patient-derived xenografts." (PMID 36461044, 2022). "A GNAS mutation, any change in the genetic sequence of GNAS, has been identified in a number of neoplasms including those of the lung, appendix, colon, pancreas, and kidney." (PMID 35052777, 2022). "Most interestingly, we identified a recurrent missense mutation in the GNAS gene, which is a novel somatic mutation and correlates with a lower tumor mutational burden." (PMID 36151521, 2022). "Next-generation sequencing (NGS) revealed other than STK11 germline mutation, the tumor also harbors GNAS somatic mutation at codon 478 and EGFR amplification." (PMID 36578081, 2022). "We recruited 145 patients, and ctDNA levels were assessed in patients with tumours carrying IDH1/2 or GNAS mutations." (PMID 34528398, 2021). "GNAS-mutated somatotroph tumours are smaller and less likely to be invasive but contribute to higher GH and IGF-1 levels." (PMID 33805450, 2021). "In comparison to AIP and GPR101 mutated PAs, GNAS-positive tumours arise in older patients and show a better response to first-generation somatostatin analogues treatment." (PMID 33805450, 2021). "ctDNA levels were assessed in 83 of the remaining 104 patients, whose tumours harboured a hotspot mutation in IDH1/2 or GNAS." (PMID 34528398, 2021). "ctDNA for IDH1/2 and GNAS mutations was detected pre‐operatively in a total of 30/81 (37%) patients harbouring the relevant hot spot mutations in their tumours." (PMID 34528398, 2021). "The GNAS p.R201C, c.601C > T variant was observed in the tumor sample of patient #11, and a gene fusion [chr5:58476419(-)::chr2:212615429(-)] showing PDE4D exon 5 fused to ERBB4 exon 5 was observed in the ACT from patient #10." (PMID 32098292, 2020). "Various pathways of progression have been reported for IPMN-related invasive PC, some of which involve mutations in KRAS, GNAS or other tumor suppressor genes." (PMID 32937962, 2020). "The result indicated that GNAS mutation mainly affect the expression level of mucin instead of tumor cell proliferation." (PMID 32700107, 2020).
tumor (continued). "From Jean’s work, IL-6 and interferon pathways were activated in GNAS-mutated tumor tissues, suggesting that GNAS enzymatic activity is necessary for IL-6/STAT3 activation." (PMID 32123532, 2020). "This review is to systemically summarize the biological background and variant features of GNAS, as well as the impacts of GNAS mutations on mucin expression, tumor cell proliferation, clinical-pathological characteristics, and prognosis of PMP." (PMID 32700107, 2020). "A complicating factor for mutation detection in IM is the mosaicism of GNAS mutations combined with hypocellularity of the tumor, where low concentrations of genomic DNA are isolated from these tissue specimens, especially in the case of biopsy material." (PMID 30736805, 2019). "Both gDNA and sDNA obtained from 10 PA patients samples were analyzed for the presence of GNAS c.601C>T and c.680A>T somatic variants in tumor tissue by direct PCR amplification of corresponding DNA fragment and subsequent Sanger sequencing." (PMID 31620080, 2019). "While SIK2 is deemed to be a tumor promoter in most cases, in the context of GNAS mutated PDA, it is supposed to be a tumor suppressor, mainly because SIK2 plays different roles in different tissue and cells, similar to cAMP/PKA signaling." (PMID 30723708, 2019). "We amplified regions of 192 somatic mutations (including SNVs and INDELs) and the KRAS and GNAS hotspot mutations from DNAs extracted from the corresponding FFPE tumor samples and validated them by deep sequencing and capillary sequencer." (PMID 31225717, 2019). "After right adrenalectomy, genetic analysis of the resected tumor revealed the somatic GNAS activating mutation, p.R201H." (PMID 30670014, 2019). "GNAS encodes the Gs-alpha subunit of G-proteins, and GNAS amplification or point mutations have been identified in approximately 10% of CRC tumours, often coinciding with KRAS mutations." (PMID 31653970, 2019). "Only one tumor with a GNAS mutation showed low expression of StAR, possibility because of the procedures used to prepare the formalin-fixed paraffin embedded (FFPE) samples." (PMID 27606678, 2016). "Four and three studies presented mean tumour size with SD or p value according to KRAS or GNAS mutation, respectively." (PMID 27512631, 2016). "The mean tumour size of IPMNs with GNAS mutation ranged from 1.234 to 3.859 cm, whereas the average size of IPMNs with wild-type GNAS ranged from 1.134 to 3.66 cm." (PMID 27512631, 2016). "We also assayed for mutations in KRAS and BRAF to determine the prevalence of coincident GNAS/KRAS or GNAS/BRAF mutations in our tumor cohort." (PMID 24498230, 2014). "GNAS is a known oncogene that was first described in growth-hormone secreting pituitary adenomas and has since been found to be mutated in a number of neoplasms, predominantly at the codon 201 hotspot." (PMID 24498230, 2014). "Several of these involve genes known to be implicated in tumorigenesis or tumor maintenance, like GNAS or HSPD1." (PMID 23537109, 2013). "According to pituitary MRI, the tumor maximum diameter (1.75 ± 0.83 vs 2.23 ± 0.89 cm, P = 0.008) and the proportion of macroadenomas (83.3 vs 96.3%, P = 0.039) were both significantly smaller in patients with GNAS mutations." (PMID 39513543, 2025). "The P8605 tumor underwent targeted cancer gene sequencing and had a mutation in GNAS." (PMID 40018643, 2025). "Although our cell-line data showed minor dsRNA formation with a trend of TE upregulation by GNAS KO, we found using a cohort of 322 DLBCL transcriptome samples that low GNAS expression was associated with strong tumor-intrinsic upregulation of retrotransposon expression." (PMID 39117798, 2024). "The relatively small VAF of GNAS mutations in our tumor samples (on average 10.7%, ranging from 2.35% to 27.91%) match our observation that the tumors contain mostly fibroblasts (supportive cells) and endothelial cells, with only a small percentage of tumor cells." (PMID 38791144, 2024).